CSRNP3 (cysteine and serine rich nuclear protein 3)
Description:
Binds to the consensus sequence 5'-AGAGTG-3' and has transcriptional activator activity. Plays a role in apoptosis (By similarity).
Synonyms: TAIP-2; FAM130A2; TAIP2; FLJ32093; PPP1R73; MBU1
Tractability: PROTAC: ubiquitination databases record sites on it.
Safety:
Unwanted effects reported when the protein is acted on. In parentheses: how it was acted on, where the effect was seen, and who reports it.
Osteonecrosis (source: ClinPGx)
Gene: Protein-coding gene on chromosome 2 (165,469,647 to 165,689,407, forward strand). Ensembl gene ENSG00000178662.
Subcellular location: Nucleus
Subcellular location (Human Protein Atlas): Nucleoli rim; Nucleoplasm
Gene Ontology:
Molecular function: DNA-binding transcription factor activity; DNA-binding transcription factor activity, RNA polymerase II-specific; sequence-specific DNA binding; DNA-binding transcription activator activity, RNA polymerase II-specific
Biological process: positive regulation of apoptotic process; positive regulation of transcription by RNA polymerase II; regulation of transcription by RNA polymerase II
Cellular component: chromatin; nucleus
Genetic constraint (gnomAD): Loss-of-function variants: 12 observed, 50.19 expected, observed/expected ratio (o/e) 0.24, 90% interval 0.15 to 0.39. The upper end of that interval is the gene's LOEUF score, 0.39, which puts it in group 1 of 6, group 1 being the genes least tolerant of losing a copy. Missense variants: 580 observed, 763.73 expected, observed/expected ratio (o/e) 0.76, 90% interval 0.71 to 0.81. Synonymous variants: 263 observed, 285.32 expected, observed/expected ratio (o/e) 0.92, 90% interval 0.83 to 1.02.
Homologues: Orthologues: chimpanzee CSRNP3 (100% identical), macaque CSRNP3 (99% identical), rabbit CSRNP3 (98% identical), guinea pig CSRNP3 (96% identical), pig CSRNP3 (96% identical), mouse Csrnp3 (94% identical), rat Csrnp3 (94% identical), dog CSRNP3 (88% identical), tropical clawed frog csrnp3 (74% identical), zebrafish CSRNP3 (58% identical), Drosophila melanogaster Axud1 (29% identical), Caenorhabditis elegans C41D11.3 (22% identical). Paralogues in human: CSRNP2 (45% identical), CSRNP1 (33% identical).
Diseases named in the same sentence as CSRNP3 in open-access papers:
CSRNP3 is named in the same sentence as 14 diseases in open-access papers, as found by Europe PMC text mining. Sharing a sentence is not in itself a finding about the gene and the disease. The quoted sentences say what the papers report.
metabolic syndrome (3 papers, 2017 to 2021). A cluster of metabolic risk factors for CARDIOVASCULAR DISEASES and TYPE 2 DIABETES MELLITUS. "CSRNP3 was found to encode a transcriptional factor for muscle development in growing pigs, and was reported as a target gene to treat obesity and metabolic syndrome in an exome-wide mediated study." (PMID 33869003, 2021). "The target gene of miR-143 encodes the cysteine and serine rich nuclear protein 3 (CSRNP3), single nucleotide polymorphisms (SNPs) of which has been identified as a novel susceptibility mark for metabolic syndrome." (PMID 32293320, 2020). "In addition, single nucleotide polymorphisms in three genes (CROT, TSC1, RIN3) and at four loci (ANKK1, ZNF804B, CSRNP3, 17p11.2) were implicated as candidate determinants of obesity and metabolic syndrome, respectively." (PMID 28445147, 2017).
clear cell renal cell carcinoma (2 papers, 2022 to 2023). "Target DEGs of miR-30c in our analysis were mostly related to the anti-apoptosis of abnormal tumor cells, including MAP3K9 in lung cancer, ST6GALNAC5 in prostate cancer, CSRNP3 in clear renal cell carcinoma, ZNF703 in breast tumors, and CLSPN in brain tumors." (PMID 36700234, 2022). "In clear cell renal cell carcinoma (ccRCC), the CSRNP3 may serve as a prognostic biomarker to predict the overall survival of patients." (PMID 36911672, 2023).
lung carcinoma (2 papers, 2022 to 2024). "Our discoveries highlight that the CSF2/lnc‐CSRNP3 relationship could be a new target for treatment to overcome osimertinib resistance in lung cancer patients." (PMID 39036343, 2024).
Obesity (2 papers, 2017 to 2021). Accumulation of substantial excess body fat. "We also identified three genes (CROT, TSC1, RIN3) as new candidate susceptibility loci for obesity as well as three genes (ANKK1, ZNF804B, CSRNP3) and chromosome 17p11.2 as new candidate loci for MetS." (PMID 28445147, 2017).
artery obstructions (1 paper, 2021). "Increased expressions of the CSRNP3, FUT10, SHD, NAV2-AS4, and hsa-mir-181 genes resulted in significance with the complexity of coronary artery obstructions or correlated with a functional cardiac benefit from bypass surgery." (PMID 34926599, 2021).
atherosclerosis (1 paper, 2021). A disease characterized by the build-up of fatty material and calcium deposition in the arterial wall resulting in partial or complete occlusion of the arterial lumen. "Recently, CSRNP3 was identified as one of eight overlapping genes between CD90pos MSCs and the atherosclerosis associated gene expression dataset of aorta and fat tissue, STARNET." (PMID 34926599, 2021).
colorectal cancer (1 paper, 2023). A primary or metastatic malignant neoplasm that affects the colon or rectum. "We found that CSRNP3 was previously found to be associated with colorectal cancer." (PMID 36911672, 2023).
coronary artery disease (1 paper, 2021). "The expressions of CSRNP3 and FUT10 were higher in the high SYNTAX score category, suggesting that lower CSRNP3 and FUT10 expression levels reflect milder or less complex coronary artery disease." (PMID 34926599, 2021).
tumor (3 papers, 2021 to 2024). "The anti‐CSF2 antibody or lnc‐CSRNP3 knockout significantly reduced the CSF2 content in mouse plasma and the lnc‐CSRNP3 expression in xenograft tissues, as well as markedly decreased the tumor volume and tumor weight." (PMID 39036343, 2024). "Meanwhile, CSRNP2 and CSRNP3 were both mostly positively associated with effector memory CD4 T cells, but not with type 2 T cells in tumor tissues." (PMID 33869003, 2021).
cancer (1 paper, 2021). A tumor composed of atypical neoplastic, often pleomorphic cells that invade other tissues. "However, the role of CSRNP3 in cancer development requires further investigation." (PMID 33869003, 2021).
CSRNP3 also shares sentences with these, for which no sentence is quoted: alcohol dependence (1 paper); brain tumors (1); breast tumors (1); prostate carcinoma (1).